ENSG00000212266
Synonyms: LOC124900444
Gene: Small nucleolar RNA gene on chromosome 1 (117,688,621 to 117,688,742, reverse strand). Ensembl gene ENSG00000212266.
Gene Ontology:
Biological process: RNA processing
Cellular component: nucleolus
Homologues: Paralogues in human: SNORA40B (92% identical), SNORA40 (91% identical), SNORA40C (87% identical).